FOXP3 (forkhead box P3)
Diseases named in the same sentence as FOXP3 in open-access papers (continued):
Sharing a sentence is not in itself a finding about the gene and the disease.
cervical carcinoma (continued). "The behavior of the FOXP3 expression during cervical cancer development was observed to increase." (PMID 36672296, 2023). "Estrogen directly stimulates FOXP3 expression and function of Tregs in cervical cancer." (PMID 37115435, 2023). "In cervical cancer, silencing of Foxp3 downregulate p16INK4a, which inhibits cell proliferation." (PMID 35326661, 2022). "We found similar mRNA levels for FOXP3 in normal cervical tissue as in cervical cancer tissue." (PMID 35087740, 2021). "In addition, a study evaluated the FoxP3+ TILs in formalin-fixed paraffin-embedded tissues from 96 cervical cancer patients." (PMID 34553029, 2021). "Both CD4+CD25+ and FoxP3+ Tregs were reported in TILs of cervical cancer." (PMID 34553029, 2021). "In addition, experiments found that in cervical cancer, the high expression of Foxp3 is not only related to poor prognosis, but also an independent prognostic factor predicting overall survival and disease-free survival." (PMID 33784955, 2021). "It was found in some studies that the increased expression of TGF-β1 and Foxp3 proteins in cervical cancer tissues may play an important role in promoting the immune escape of cervical cancer cells and the formation and metastasis of cervical cancer." (PMID 33336057, 2020). "On the contrary, neoadjuvant chemotherapy for cervical cancer resulted in a decreased FOXP3+ density, resulting in an elevated intratumoral CD8/FOXP3 ratio that might confer a favorable clinical outcome." (PMID 32974178, 2020). "In addition, lncRNA MALAT1 and SNHG12 promoted proliferation of multiple myeloma and glioma targeting FOXP1, while lncRNA UFC1 and 7SL enhanced proliferation of cervical cancer and osteosarcoma, targeting FOXP3 and FOXP4, respectively." (PMID 31815635, 2019). "Previous studies showed that the number of FOXP3+ regulatory T-cells that could suppress the innate and adaptive immunity systems was higher in cervical cancer compared to other types of tumors and suppressed immune responses." (PMID 31842422, 2019). "Therefore, the CCL22+ infiltrating cells or the combination of CCL22 (+) and FOXP3 (+) cells are novel biomarkers that can be potentially used for cervical cancer prognosis." (PMID 31842422, 2019). "CCL22 expression is positively correlated with FoxP3 expression in cervical cancer." (PMID 31842422, 2019). "However, Tang and his colleagues demonstrated that FOXP3 is positively correlated with VEGF-C in lymphangiogenesis of cervical cancer." (PMID 31815635, 2019). "The role of FoxP3-expressing CD8+ T cells in cervical cancer is controversial." (PMID 31616965, 2019). "Our study revealed a correlation between the expression of CCL22 and FOXP3 in cervical cancer." (PMID 31842422, 2019). "Nevertheless, until now, no research has reported the association of Foxp3 expression with lymphangiogenesis of cervical cancer." (PMID 28923073, 2017). "Recent observations revealed Foxp3 participated in the development of cervical cancer." (PMID 28923073, 2017). "In addition, we evaluated the association between Foxp3 and VEGF-C expression and lymphangiogenesis of cervical cancer evaluated by lymphatic vessel density." (PMID 28923073, 2017). "Foxp3 was found not only in nuclear of lymphocytes but also in cytoplasm of cervical cancer cells." (PMID 28923073, 2017). "More importantly, Foxp3 might promote lymphatic vessel formation in cervical cancer correlated with VEGF-C expression." (PMID 28923073, 2017). "Furthermore, Foxp3 had a significant role in facilitating lymphatic metastasis of cervical cancer, and high Foxp3 expression in the cervical cancer predicted a poor prognosis." (PMID 28923073, 2017). "Immunohistochemical staining of Foxp3 was performed in 50 cervical cancer cases." (PMID 28923073, 2017). "CD4+CD25+Foxp3+ Tregs play an important role in the pathogenesis of cervical carcinoma." (PMID 27115350, 2016).
cervical carcinoma (continued). "The present study demonstrated that HMGB1 might be correlated positively with Foxp3 expression and both of them were significantly enhanced in cervical cancer tissues." (PMID 24837834, 2014). "Moreover, we also observed the correlation of Tc17 cells with Foxp3-expressing T cells in cervical cancer tissues,Foxp3-expressing T cells mediate strong immune-suppressive activity on T cell responses." (PMID 24523865, 2014). "HMGB1, forkhead/winged helix transcription factor p3 (Foxp3), IL-2, and IL-10 protein expression was analyzed in 100 cervical tissue samples including cervical cancer, cervical intraepithelial neoplasia (CIN), and healthy control samples using immunohistochemistry." (PMID 24837834, 2014). "CCL22 expression is positively correlated with FoxP3 expression, could polarize TAMs toward M2a macrophages and may represent a novel prognostic marker and therapeutic target for the treatment of cervical cancer." (PMID 37894319, 2023). "Additionally, it was found that FoxP3 had a high expression in cervical cancer and could promote the cancer cells’ metastasis through immune escape." (PMID 37569676, 2023). "CD3+ tumor infiltrating T cells (TILs), CD45RO+ TILs, CD4+ TILs, CD8+ TILs, FOXP3+ TILs (regulatory T cells, Tregs), CD68+ tumor associated macrophages (TAMs), CD163+ TAMs, and PD-L1+ tumor cells were immunostained in formalin-fixed paraffin-embedded (PPFE) tissues from 96 cervical cancer patients." (PMID 31616592, 2019). "In conclusion, our work suggested that assessment of CD45RO+ TILs in the invasive margin area and FOXP3+ TILs in the central tumor area of cervical cancer tissue might be helpful for choosing therapeutic strategies and prognostication for cervical cancer with radical hysterectomy." (PMID 31616592, 2019). "Furthermore, Foxp3 has a vital function in the lymphatic metastasis of cervical cancer." (PMID 28923073, 2017). "However, compared with the healthy control group, the percentages of CD4+ CD25+ Treg, CD4+CD25+CD127- Treg, CD4+IL17+ Th17, CD4+CD25+Foxp3+, CD4+CD25- Foxp3+, CD8+CD25+CD127-Treg and CD8+CD25+Foxp3 were significantly higher in the cervical cancer group and the CIN group." (PMID 23587428, 2013). "In cervical cancer, artesunate inhibits in situ tumor growth and exerts antitumor effects by suppressing PGE2 production in CaSki and HeLa cells and downregulating Foxp3 expression in T cells." (PMID 41458964, 2025). "We propose that targeting the CXCL12‐CXCR4 axis, SNAIL, FOXP3, and its rs3761549 variant in an oncogenic HPV/XPO5 TME—characterized by high M2‐TAM infiltration and STAT3/NF‐κB upregulation—may help counteract immunosuppression and metastasis in cervical cancer." (PMID 41263059, 2025). "A genetic analysis of cervical cancer tumor tissue was conducted to assess the expression of STAT3, Snail, PD‐1, HPV16, HPV18, FOXP3, EXPORTIN 5 (XPO5), CXCR4, CXCL12, and CD8." (PMID 41263059, 2025). "The staining of TGFβ, PD-L1, IL-10, FOXP3, IL-17, and MIF was cytoplasmic and present in 25%, 9.4%, 56.2%, 7.2%, 76.3%, 86.1%, and 85.2%, respectively, of the cervical cancer cases." (PMID 39061137, 2024). "A comparison of sentinel nodes and distant lymph nodes in early cervical cancer identified a significant increase in CD8 T cells, and expression of FoxP3 and PD‐1 in SN compared with distant lymph nodes." (PMID 34165864, 2022). "Here, we assessed the expression of PD-1 and CD39 in circulating memory (CD45RA-) conventional (Tconv; FOXP3-) CD4 T cells from head and neck squamous cell carcinoma (HNSCC) and cervical cancer (CC) patients and from healthy donors (HDs)." (PMID 35954341, 2022). "The expression of FOXP3 and IL2RA, the marker genes to calculate the relative infiltration of Tregs, were both evenly expressed in healthy cervical cancer tissue and cervical cancer tissues." (PMID 35087740, 2021). "In cervical cancer, ARS inhibited prostaglandin production, which in turn led to the decreased expression of Foxp3 in T cells." (PMID 33117153, 2020).
cervical carcinoma (continued). "The IRS of CCL22 expressed in cervical cancer cells was evaluated and the number of CCL22+ and FOXP3+ cells was counted." (PMID 31842422, 2019). "In cervical cancer, the CCL22 mRNA levels of neoplastic foci and tumor periphery is positively correlated with FOXP3." (PMID 31842422, 2019). "We phenotyped and compared various tumor-infiltrating T-cell subsets using CD3, CD8, FoxP3, Tbet, and Ki67 as markers in multiplex IHC on pre- and post-NACT tumor samples from patients with cervical cancer." (PMID 31616965, 2019). "This correlation was defined by calculating the IRS of CCL22 expression in cervical cancer cells and counting the number of CCL22+ and FOXP3+ cells." (PMID 31842422, 2019). "In our study, the density of FOXP3+ TILs in the central tumor area demonstrated negative correlation with risk stratification in a significant level (P = 0.009), which suggest the importance of Tregs as both prognostic biomarkers and therapeutic targets for cervical cancer patients." (PMID 31616592, 2019). "A particular significance correlation was found between CXCL12 and FOXP3 in cervical neoplastic lesion, suggesting that high levels of CXCL12 leads to retention or accumulation of FOXP3+ T cells in progressing cervical cancer." (PMID 30227860, 2018). "However, it is unclear whether Foxp3 is correlated with lymphangiogenesis of cervical cancer." (PMID 28923073, 2017). "In this experiment, expression of Foxp3 and VEGF-C was detected in 50 cervical cancer samples by immunohistochemistry." (PMID 28923073, 2017). "The FoxP3, CCL22 and CCR4 mRNA level in local immune microenvironment of normal cervix was lower than that in cervical cancer." (PMID 28086903, 2017). "The correlation analysis indicated that in immune microenvironment of cervical cancer, the mRNA level of CCL22 and CCR4 was strengthened as the Foxp3 mRNA level increased and vice verse." (PMID 28086903, 2017). "In this study, we investigated the localization and distribution of FoxP3+-, CD8+-, HLA-DR+- and PD-L1+ myeloid cells in all pelvic lymph nodes from five SCC cervical cancer patients with lymph node metastases." (PMID 26431490, 2015). "In addition, we identified a peri-tumoral area with immunosuppressive FoxP3+ Tregs and PD-L1+ myeloid cells accumulation whereas only a minimal number of immune cells were observed infiltrating into the tumoral areas in lymph nodes from patients with cervical cancer." (PMID 26431490, 2015). "In summary, our study concluded that elevations of CD4+CD25+CD127lo/-Treg, Foxp3+ Treg, CD8+ Treg and Th17 cells exsit in peripheral blood of Uygur patients with cervical cancer." (PMID 23587428, 2013). "In post-NACT patients, the peritumoral Foxp3+ T cell to intratumoral CD8+ T cells ratio serves as a critical predictor of survival, with lower ratios being positively correlated with improved PFS and overall survival in locally advanced cervical cancer." (PMID 40539072, 2025). "Interestingly, our results showed a strong association correlation between CD163 + CD204 + M2TAM, via STAT3/NF-κB pathways and the expression of CD25, FOXP3, MIF, and IL-17 in 56.2%, 76.3%, 85.2%, and 86.1%, respectively, of 691 patients with cervical cancer." (PMID 39061137, 2024). "Some unconventional T cells and non-T cells, including NK, CD4+CD25+ or FoxP3+ Tregs, Th17 cells, γ-δT cells, and acrophages, have also been used in adoptive immunotherapy for cervical cancer." (PMID 37180106, 2023). "On the one hand, it was reported that cervical cancer cells could secrete indoleamine 2,3-dioxygenase (IDO) to recruit FOXP3+ regulatory T-cells." (PMID 31842422, 2019). "Besides, artesunate also exerts immunosuppression through forkhead box P3 (Foxp3) down-regulation in T cells and decreases prostaglandin E2 (PGE2) production in human cervical cancer Caski and HeLa cells." (PMID 31719837, 2019).
cervical carcinoma (continued). "We speculated that reduction of Foxp3 by chemotherapy may diminish the immunologic suppression, thus resulting in a high pCR rate in cervical cancer with both CD8 and Foxp3 infiltration." (PMID 30474571, 2018). "More studies will be necessary, however, in order to demonstrate the lack of Foxp3 in expanded CD4+NKG2D+ T cells from cervical cancer patients." (PMID 26486970, 2015). "In addition, it has also been shown that FoxP3 regulates the expression of LINC00885, and that high expression of FoxP3 could promote cervical cancer cells’ proliferation and the activation of EMT pathways." (PMID 37569676, 2023). "We evaluated Treg frequency in dual infection of HR HPV and HIV coinfection using phenotypic markers, CD4, CD25 and intracellular Foxp3, in the peripheral blood of 51 cervical cancer and 46 non-cervical cancer participants and evaluated the effect of HIV on regulatory T cell proportion." (PMID 37670247, 2023). "The double positive expression of VISTA and Foxp3 indicate the worst prognosis of cervical cancer patients, compared to the single negative group; the survival analysis shows that the single positive expression of VISTA has the worst average survival (35.114 ± 2.828 vs. 51.486 ± 1.403 months)." (PMID 35831836, 2022). "In cervical cancer, VISTA is found expressed in the membrane and cytoplasm of tumor cells, VISTA may co-express with Foxp3, Foxp3 is expressed in CIN I-III, but VISTA only expresses in CIN II-III, the co-expression of which indicates the prognosis of cervical patients (see part 5.2)." (PMID 35831836, 2022). "Therefore, we concluded that both genes FOXP3 (transcriptional factor) and IL2RA (cytokine) have an important function in healthy cervical tissue samples and cannot be used as accurate marker genes to identify Tregs cells in cervical cancer." (PMID 35087740, 2021). "Furthermore, low levels of peritumoral Foxp3+ cells before treatment was able to identify a group of patients who were highly sensitive to NACT, while the intratumoral CD8+/ peritumoral FoxP3+ ratio in residual tumors was the predictor of DFS and OS for locally advanced cervical cancer patients." (PMID 30474571, 2018). "Hence it is reasonable to speculate that up-regulation of Foxp3+ Treg cells in cervical CIN and cervical cancer patients will lead to weakened immune surveillance function." (PMID 23587428, 2013). "Therefore, in the present study we analyzed the distribution and localization of FoxP3+ Tregs, CD8+ T cells, HLA-DR+- and PD-L1+ myeloid cells in all pelvic lymph nodes, including LN+ and LN−, removed during primary surgery of five patients with cervical cancer." (PMID 26431490, 2015). "As shown in, the expressions of Foxp3 (A) and VISTA (B) in mouse cervical cancer tissues and adjacent tissues were not significantly different in each group." (PMID 33784955, 2021). "In cervical cancer, however, the correlation between protein expression levels of CCL22 and FOXP3, and the cell source of CCL22 have not been determined." (PMID 31842422, 2019). "In summary, these results showed that the level pattern of mRNA of FoxP3, CCL22/CCR4, OX40L/OX40 and Smad3 in cervical cancer immune microenvironment distinctly differed from that in normal cervix." (PMID 28086903, 2017). "Though one study of cervical cancer reported a significant decrease in FoxP3+ T cells in the TME after NACT, they stained only a single marker, FoxP3, for IHC and did not identify these FoxP3-expressing cells using other markers." (PMID 31616965, 2019).
colon carcinoma (85 papers, 2010 to 2025). "By contrast, however, it was shown recently that a high density of Foxp3+ Tregs in tumor tissue of patients with colon cancer was associated with an improved survival." (PMID 20205946, 2010). "A high density of infiltrating FoxP3+ Tregs has been shown to be associated with an adverse prognostic impact in some tumor types, yet a favorable impact in others, including in colon cancers." (PMID 22879926, 2012). "However, there are also instances where Foxp3+ TILs have been linked to a favorable prognosis such as e.g. in colon cancer, Hodgkin lymphoma and HNSCC." (PMID 22701698, 2012). "For example, CD39+ Tregs in gastric and colon cancer were identified as a potentially important immunosuppressive subset, and a higher number of TIGIT+Foxp3+ γδ T cells was associated with poor overall survival in patients with acute myeloid leukemia (AML)." (PMID 36901957, 2023). "Confirmatory IL2RB immunohistochemistry (IHC) analysis in a large MSI-H colon cancer tissue microarray (TMA; n = 115) revealed sensitive, specific staining of a subset of lymphocytes and a strong association with FOXP3+ lymphocytes (P < 0.0001)." (PMID 33928242, 2021). "Higher tumoral expression of Foxp3, IL-17, IL1-beta, IL-6 and TGF-β was associated with the MSS phenotype, and the IL-17 T/TN (colon cancers/autologous normal colon mucosa) ratio was higher in MSS tissues than in MSI-H tissues." (PMID 35095898, 2021). "Thermodesulfovibrio has been recently discussed to play a role in the modulation of FOXP3 and IL-17 involved in immune tolerance in colon cancer." (PMID 33659025, 2021). "As shown in the interaction network, immune-related gene PLCG2 and IGF1, which are up-regulated in colon tumor samples, have significantly strong correlation with several TFs: FOXP3, IKZF1, CBX7, LMO2, MEF2C, EPAS1 and MAF." (PMID 33996273, 2021). "In contrast, the Foxp3+ cells were elevated in the colonic tumors of the STAT6−/− PC61 animals during the late stages of CAC development, compared to the STAT6−/− CAC and WT PC61 mice." (PMID 33919941, 2021). "Based on our observation, the frequency of these FOXP3-expressing cells was much higher in draining lymph nodes from patients with BC compared to other cancers including breast and colon carcinomas." (PMID 33305045, 2020). "From the pooled results of colon cancer, the positive prognostic value of FOXP3+ T cell in IM for OS was inconsistent from the results of a previous meta-analysis, which illustrated that high FOXP3+ T cell infiltrates were not correlated with improved OS." (PMID 31118034, 2019). "in addition, FoxP3+RORγt+ IL-17-producing T cells as an unstable lineage have detected in colon cancer proposed that they can be originated from FoxP3+Treg cells." (PMID 31024835, 2019). "In our study, we found specific DNA hypomethylation of FOXP3-TSDR in CD4+ T cells from colon tumor tissues as compared with normal colonic tissues." (PMID 30013992, 2018). "To confirm that the abnormally increased STAT5 and TET2 bind more strongly to FOXP3-TSDR in CD4+ T cells from colon tumor tissues compared with which from normal tissues, we performed ChIP-qPCR analysis using anti-STAT5 and TET2 antibody." (PMID 30013992, 2018). "The FOXP3-TSDR was found to be significantly hypomethylated in CD4+ T cells from colon tumor tissues as compared with normal colonic tissues." (PMID 30013992, 2018). "All of these data confirmed the negative regulatory role of FOXP3 on the self-renewal ability of colon cancer stem cells." (PMID 28591725, 2017). "In the murine model of colitis-associated colon cancer (CAC), CD4+ Foxp3+ Tregs are crucial for the control of the inflammatory process." (PMID 28938014, 2017). "Last but not least, in our manuscript, positive control specimens for PD-L1 and Foxp3 IHC were created by human placenta and human colon cancer." (PMID 27602763, 2016).